NUP54 (nucleoporin 54)
Description:
Component of the nuclear pore complex, a complex required for the trafficking across the nuclear membrane.
Synonyms: DYT37
Tractability: Antibody: UniProt places it where antibodies can reach, with medium confidence. PROTAC: ubiquitination databases record sites on it; its protein half-life has been measured.
Gene: Protein-coding gene on chromosome 4 (76,107,562 to 76,148,509, reverse strand). Ensembl gene ENSG00000138750.
Subcellular location: Nucleus, nuclear pore complex; Nucleus membrane
Subcellular location (Human Protein Atlas): Nucleoplasm
Pathways (Reactome):
Disease: Defective TPR may confer susceptibility towards thyroid papillary carcinoma (TPC); HCMV Early Events; HCMV Late Events; NEP/NS2 Interacts with the Cellular Export Machinery; NS1 Mediated Effects on Host Pathways; Nuclear import of Rev protein; Rev-mediated nuclear export of HIV RNA; SARS-CoV-2 activates/modulates innate and adaptive immune responses; Transport of Ribonucleoproteins into the Host Nucleus; Viral Messenger RNA Synthesis; Vpr-mediated nuclear import of PICs
Metabolism of RNA: Transport of Mature mRNA Derived from an Intronless Transcript; Transport of Mature mRNA derived from an Intron-Containing Transcript; Transport of the SLBP Dependant Mature mRNA; Transport of the SLBP independent Mature mRNA; snRNP Assembly; tRNA processing in the nucleus
Metabolism of proteins: SUMOylation of DNA damage response and repair proteins; SUMOylation of DNA replication proteins; SUMOylation of RNA binding proteins; SUMOylation of SUMOylation proteins; SUMOylation of chromatin organization proteins; SUMOylation of ubiquitinylation proteins
Metabolism: IP3 and IP4 transport between cytosol and nucleus; IP6 and IP7 transport between cytosol and nucleus; IPs transport between nucleus and cytosol; Regulation of Glucokinase by Glucokinase Regulatory Protein
Cell Cycle: Nuclear Pore Complex (NPC) Disassembly; Postmitotic nuclear pore complex (NPC) reformation
Cellular responses to stimuli: Regulation of HSF1-mediated heat shock response
Immune System: ISG15 antiviral mechanism
Gene Ontology:
Molecular function: protein binding; structural constituent of nuclear pore
Biological process: NLS-bearing protein import into nucleus; nuclear pore organization; nucleocytoplasmic transport; protein localization to nuclear inner membrane
Cellular component: nuclear envelope; nuclear membrane; nuclear pore; nuclear pore central transport channel
Genetic constraint (gnomAD): Loss-of-function variants: 18 observed, 43.71 expected, observed/expected ratio (o/e) 0.41, 90% interval 0.28 to 0.61. The upper end of that interval is the gene's LOEUF score, 0.61, which puts it in group 2 of 6, group 1 being the genes least tolerant of losing a copy. Missense variants: 393 observed, 493.77 expected, observed/expected ratio (o/e) 0.8, 90% interval 0.73 to 0.87. Synonymous variants: 170 observed, 183.39 expected, observed/expected ratio (o/e) 0.93, 90% interval 0.82 to 1.05.
Homologues: Orthologues: macaque NUP54 (100% identical), pig NUP54 (97% identical), dog NUP54 (97% identical), rabbit NUP54 (96% identical), mouse Nup54 (96% identical), rat Nup54 (96% identical), chimpanzee NUP54 (90% identical), guinea pig NUP54 (85% identical), tropical clawed frog nup54 (81% identical), Drosophila melanogaster Nup54 (38% identical), Caenorhabditis elegans npp-1 (24% identical).
Diseases named in the same sentence as NUP54 in open-access papers:
NUP54 is named in the same sentence as 6 diseases in open-access papers, as found by Europe PMC text mining. Sharing a sentence is not in itself a finding about the gene and the disease. The quoted sentences say what the papers report.
HIV-1 infection (3 papers, 2018 to 2023). The type species of lentivirus and the etiologic agent of acquired immunodeficiency syndrome (AIDS). "While the loss of Nup54 and Nup58 elevated infection of WT HIV-1, N74D HIV-1, and P90A HIV-1, removal of Nup62 had a larger positive effect on WT HIV-1 infection." (PMID 37355754, 2023). "By contrast, depletion of Nup62 or Nup214 elevated WT HIV-1 infection, and Nup54 and Nup58 knockdown enhanced infection of both WT and CA mutant HIV-1." (PMID 37355754, 2023). "Removal of Nup62 subcomplex members (Nup54, Nup58, and Nup62), which are FG-Nups that form a meshwork in the central channel of the pore restricting the flow of cargo larger than 5 nm in diameter, generally elevated both WT and N74D HIV-1 infection." (PMID 37355754, 2023). "Furthermore, our data suggest a potential link between IFNβ, decreased TGFβ signaling (SMAD4), increased unfolded protein response (VIMP and SEP15) and increased DNA damage (NUP54 and MUS81) in chronic HIV-1 infection." (PMID 33064743, 2020). "In fact, several Nup depletions (NUP205, NUP62, NUP54, and NUPL1) had larger effects on HIV-1 infection in non-dividing as compared to dividing HOS cells." (PMID 30084827, 2018). "HIV-2 and SIVmac infection were inhibited by many Nup depletions and both were modestly sensitive to depletions of a number of Nups that did not affect HIV-1 infection (e.g. NUP155, TPR, NUP62, NUP54, NUPL1." (PMID 30084827, 2018).
breast carcinoma (1 paper, 2020). "For example, consider the heterozygous eQTL variant (rs10654) mapping to the 3′ UTR of the NUP54 gene in both normal and tumor samples of breast cancer patient 2 (TCGA-BH-A0BW)." (PMID 32064050, 2020).
Dystonia (1 paper, 2025). An abnormally increased muscular tone that causes fixed abnormal postures. "Additionally, mutations in NUP54—classified as DYT-NUP54 (DYT37)—have been associated with isolated dystonia accompanied by striatal lesions, highlighting a potential neuroimaging biomarker that warrants further investigation." (PMID 40722357, 2025).
infection (4 papers, 2018 to 2024). The state of being infected such as from the introduction of a foreign agent such as serum, vaccine, antigenic substance or organism. "Infection by HIV-1N57S was strongly inhibited by CsA in HT1080 cells and Nup depletions partly (e.g. NUP62, NUP54, NUPL1) or nearly completely (e.g. NUP155, NUP205) abolished this CsA sensitivity." (PMID 30084827, 2018). "The CsA dependence of HIV-1A92E infection in HeLa cells was exaggerated by some Nup knockdowns (e.g. NUP93, NUP205, NUP54, NUP153) while other knockdowns reduced or eliminated the enhancing effects of CsA (e.g. NUP98, NUP107, NUP155)." (PMID 30084827, 2018). "Notably, 9 nucleoporins (NUP58, NUP214, NUP98, NUP54, NUP62, NUP88, NUP153, POM121/NUP121 and RANBP2/NUP358) and the mRNA export factor Rae1 were present in both the CebN infection and transfection interactomes." (PMID 38712050, 2024).
cancer (3 papers, 2018 to 2024). A tumor composed of atypical neoplastic, often pleomorphic cells that invade other tissues. "In cancers, NUP54 induces nuclear import of coactivator-associated arginine methyltransferase 1 (CARM1) and, consequently, transcriptional activation and neurogenic locus notch homolog protein 2 (Notch2) methylation, thereby accelerating GC cell proliferation and tumorigenesis." (PMID 39080077, 2024). "Diseases associated with NUP54 include early onset dystonia, cancers, psoriasis, and ALS." (PMID 39080077, 2024). "Some of these genes (e.g. CENPF, MLKL, TFDP1, MCF2L) have a known influence on cancer, while others (e.g. NUP54, BBS1 and HTT) have been superficially studied under the tumoral context." (PMID 34316711, 2021). "T24 (bladder), BT549 (breast), MCF7 (breast) and DU145 (prostate) cancer cells also displayed increased sensitivity to IR upon Nup54 KD." (PMID 29986057, 2018). "However, NUP54-depleted cells also exhibited increased formation of chromosomal aberrations arising from replicated DNA, suggesting that Nup54 may also have a cancer suppressive effect by maintaining gene stability." (PMID 39080077, 2024).
NUP54 also shares sentences with these, for which no sentence is quoted: tumor (2 papers).